EMILIN2 (elastin microfibril interfacer 2)
Description:
May be responsible for anchoring smooth muscle cells to elastic fibers, and may be involved not only in the formation of the elastic fiber, but also in the processes that regulate vessel assembly. Has cell adhesive capacity.
Synonyms: FLJ33200; FOAP-10; EMILIN-2
Tractability: Antibody: its Gene Ontology location is reachable by antibodies, with high confidence; UniProt places it where antibodies can reach, with medium confidence; UniProt predicts a signal peptide or a membrane-spanning region. PROTAC: its protein half-life has been measured.
Gene: Protein-coding gene on chromosome 18 (2,846,930 to 2,916,003, forward strand). Ensembl gene ENSG00000132205.
Subcellular location: Secreted, extracellular space, extracellular matrix
Pathways (Reactome):
Extracellular matrix organization: Molecules associated with elastic fibres
Gene Ontology:
Molecular function: protein binding; extracellular matrix constituent conferring elasticity
Biological process: negative regulation of cell migration; positive regulation of angiogenesis; positive regulation of apoptotic process; positive regulation of defense response to bacterium; positive regulation of platelet aggregation; cell adhesion mediated by integrin; regulation of blood pressure; regulation of cell population proliferation; positive regulation of blood coagulation; positive regulation of multicellular organismal process
Cellular component: extracellular matrix; extracellular region; elastic fiber; EMILIN complex; microfibril
Genetic constraint (gnomAD): Loss-of-function variants: 70 observed, 81.61 expected, observed/expected ratio (o/e) 0.86, 90% interval 0.71 to 1.05. The upper end of that interval is the gene's LOEUF score, 1.05, which puts it in group 4 of 6, group 1 being the genes least tolerant of losing a copy. Missense variants: 1,405 observed, 1,316.8 expected, observed/expected ratio (o/e) 1.07, 90% interval 1.02 to 1.12. Synonymous variants: 580 observed, 530.16 expected, observed/expected ratio (o/e) 1.09, 90% interval 1.02 to 1.17.
Homologues: Orthologues: chimpanzee EMILIN2 (98% identical), macaque EMILIN2 (94% identical), rabbit EMILIN2 (81% identical), pig EMILIN2 (80% identical), rat Emilin2 (76% identical), dog EMILIN2 (75% identical), mouse Emilin2 (74% identical), guinea pig EMILIN2 (62% identical), tropical clawed frog emilin2 (45% identical), zebrafish emilin2a (32% identical), zebrafish emilin2b (25% identical). Paralogues in human: EMILIN1 (23% identical), EMILIN3 (17% identical), MMRN1 (14% identical), MMRN2 (13% identical).
Diseases named in the same sentence as EMILIN2 in open-access papers:
EMILIN2 is named in the same sentence as 60 diseases in open-access papers, as found by Europe PMC text mining. Sharing a sentence is not in itself a finding about the gene and the disease. The quoted sentences say what the papers report.
gastric cancer (7 papers, 2018 to 2025). A primary or metastatic malignant neoplasm involving the stomach. "Notably, the expression of EMILIN2 is consistently and markedly suppressed in gastric cancer, but high levels of this glycoprotein are linked to abnormal vascular density." (PMID 33543032, 2020). "In addition, since EMILIN-2 modulates the Wnt/β-catenin signaling pathway which affects the behavior of gastric cancer cells, the loss of EMILIN-2 expression may also display a direct effect of gastric cancer cell growth and progression." (PMID 30544909, 2018). "For example, EMILIN1 suppresses tumor growth, and deregulation of EMILIN2 in gastric cancer promotes tumor growth and angiogenesis." (PMID 38971308, 2024). "In some solid tumors, such as gastric cancer, breast cancer, EMILIN2 can play essential functions in the tumor microenvironment, affecting tumor growth by directly binding epidermal growth factor receptor (EGFR) and lymphangiogenesis." (PMID 32175193, 2020). "We provided evidence that the expression of Multimerin-2 and EMILIN-2 are significantly altered in a number of gastric cancer patients." (PMID 30544909, 2018). "In conclusion, in this study we characterized the expression of EMILIN-1, Multimerin-2 and EMILIN-2 in the gastric normal mucosa and in gastric cancer." (PMID 30544909, 2018). "In our in vitro studies we showed that EMILIN-2 favored tube formation in the context of gastric cancer." (PMID 30544909, 2018). "While its function in non-small cell lung tumors is not currently known, EMILIN2 has been associated with poor prognosis in gastric cancer where it modulates cancer cell apoptosis and tumor angiogenesis." (PMID 36404344, 2022). "For example, EMILIN2 expression in gastric cancer was found to be related to angiogenesis." (PMID 36544490, 2022). "In gastric cancer, EMILIN2 regulates the proliferation of cancer cells through apoptosis." (PMID 36544490, 2022). "Also, recent studies have confirmed that the appearance of Multimerin-2 and EMILIN-2 is significantly altered in gastric cancer patients and EMILIN2 has a bidirectional role in tumor micro environments." (PMID 32175193, 2020). "The authors further discovered that EMILIN2 has a dual functionality in gastric cancer." (PMID 33543032, 2020). "In particular, Multimerin-2 and EMILIN-2 affect angiogenesis and vascular efficiency, whereas EMILIN-1 affects lymphangiogenesis, which may also play a role in gastric cancer development representing an important route for metastatic dissemination." (PMID 30544909, 2018).
breast carcinoma (4 papers, 2010 to 2022). "Lastly and most importantly methylation of EMILIN2 was associated with poorer clinical outcome in breast cancer and was strongly associated with estrogen receptor as well as progesterone receptor positive breast cancers." (PMID 20205715, 2010). "The most interesting finding in the breast cancer cohort was that the methylation of EMILIN2 was associated with relapse (P = 0.031), presence of lymph node metastases (P = 0.047), with ER and PR positive tumours (P = 0.0009; 0.0082 respectively) and poor relapse free survival (P = 0.041)." (PMID 20205715, 2010). "In addition, methylation of EMILIN2 is associated with poor outcome in breast cancer." (PMID 24165089, 2013). "Since we had previously shown that EMILIN-2 attenuates the Wnt/β-catenin signaling pathway in breast cancer cells, we next verified if tumors from Emilin-2−/− mice displayed an increased activation of this pathway." (PMID 35148799, 2022). "In our cohort of breast cancer cases, EMILIN2 methylation also correlated with lymph node metastases, relapse and poor survival, hence EMILIN2 methylation is associated with less favourable prognosis." (PMID 20205715, 2010). "It will be of interest to analyse larger sample numbers to determine if EMILIN2 methylation status can be utilised as a prognostic marker in breast cancer." (PMID 20205715, 2010). "Our findings indicate that methylation of EMILIN2, CIDE-A and FBLN2 are associated with positive estrogen and or progesterone receptor status, this may help in further refining breast cancers that are more likely to benefit from endocrine therapy." (PMID 20205715, 2010). "In summary we have identified 5 (EMILIN2, SALL1, DBC1, FBLN2, CIDE-A) genes that demonstrated frequent tumour acquired methylation in breast cancer." (PMID 20205715, 2010). "EMILIN2 is located at 18p11.3 in a region showing LOH in NSCLC, CRC and breast cancer." (PMID 20205715, 2010).
colorectal cancer (4 papers, 2010 to 2022). A primary or metastatic malignant neoplasm that affects the colon or rectum. "EMILIN2 was methylated in 33% colorectal carcinomas (CRC) and in 32% adenomas, whilst only 1.2% of corresponding normal tissues demonstrated any methylation." (PMID 20205715, 2010). "We next hypothesized that EMILIN-2 could influence colorectal cancer cell behavior impinging on other molecular mechanisms." (PMID 35148799, 2022). "In addition, EMILIN2 and SALL1 also show frequent methylation in colorectal cancer and FBLN2 shows frequent tumour-specific methylation in prostate cancer." (PMID 20205715, 2010). "In addition we found that EMILIN2, FBLN2 and SALL1 were also frequently methylated in other common epithelial cancers, EMILIN2 and SALL1 in colorectal cancer and FBLN2 in prostate cancer." (PMID 20205715, 2010).
glioma (4 papers, 2020 to 2023). A benign or malignant brain and spinal cord tumor that arises from glial cells (astrocytes, oligodendrocytes, ependymal cells). "EMILIN2 was identified as an independent prognostic biomarker that could be associated with the malignancy and development of gliomas, with high expression predicting a poor prognosis." (PMID 37644433, 2023). "For example, high EMILIN2 expression led to poor prognosis in adrenocortical carcinoma, ccRCC, brain bower grade glioma, testicular germ cell tumors and uveal melanoma (p < 0.05)." (PMID 36544490, 2022).
thrombosis (3 papers, 2011 to 2015). "Our interest in EMILIN2 (E2) arose from a screen for genes associated with thrombosis." (PMID 25658937, 2015). "EMILIN2, Elastin Microfibril Interface Located Protein2, was identified as a candidate gene for thrombosis in mouse and human quantitative trait loci studies." (PMID 25658937, 2015). "The objective of this study was to determine whether EMILIN2 could play a role in thrombosis." (PMID 21569335, 2011). "We identified EMILIN2, with a high homology to EMILIN1, in the QTL on chromosome 17, in the Hmtb8 locus and found a thrombosis phenotype." (PMID 24147020, 2013).
adenoma (2 papers, 2010 to 2022). A neoplasm arising from the epithelium. "Nonetheless, the presence of adenomas displaying villous histological features or severe epithelial dysplasia, both associated to a greater propensity to develop carcinomas, were more frequent in Emilin-2−/− mice." (PMID 35148799, 2022).
glioblastoma (2 papers, 2019 to 2024). The most malignant astrocytic tumor (WHO grade IV). "In contrast, elastin microfibril interfacer 2 (Emilin2), guanine deaminase (GDA), haptoglobin (Hp) and selectin L (Sell) were enriched in macrophages/monocytes in RCAS and GL261 mouse models of glioblastoma." (PMID 38712663, 2024).
leukaemia (2 papers, 2010 to 2022). "Of note, based on the analysis of RNA expression data in leukemia precursor cells, in AML cells and in the BM of AML patients, Emilin2 belongs to the group of most deregulated genes in AML patients." (PMID 35012633, 2022). "In addition, studies aimed at the characterization of the transcription profiles of ECM-related genes in AML patients identified Emilin2 as part of the signature of leukemia precursor cells and AML, thus pointing at an involvement of Emilin-2 in AML development." (PMID 35012633, 2022).
melanoma (2 papers, 2021 to 2022). A malignant, usually aggressive tumor composed of atypical, neoplastic melanocytes. "We verified that the EMILIN2 expression is variable among melanoma patients and is associated with the response to PD-L1 inhibitors." (PMID 34299131, 2021). "We verified that EMILIN-2 modulates PD-L1 expression in melanoma cells through indirect immune-dependent mechanisms." (PMID 34299131, 2021). "In the present work, we showed that the expression of EMILIN2, which in melanoma is regulated by methylation, is variable among the patients and associated with the efficacy of anti-PD-L1 therapy." (PMID 34299131, 2021). "In melanoma, EMILIN-2 promotes angiogenesis by triggering IL-8 expression via the EGF/EGFR pathway, affecting vessel development and functionality." (PMID 34299131, 2021). "Moreover, by analyzing a well-established preclinical murine melanoma model, we demonstrated that Emilin2 serves as a regulator of PD-L1 expression." (PMID 34299131, 2021). "Although not significant, there was a trend that high EMILIN2 expression levels were associated with increased overall survival in two different melanoma patient cohorts." (PMID 34299131, 2021). "Another ECM molecule modulating the TME in melanoma is EMILIN-2." (PMID 34299131, 2021). "It is possible to speculate that the altered angiogenesis due to EMILIN2 loss could be overtaken by the activation of Th1 lymphocytes which, in turn, among other cytokines, secrete IFN-γ, with a consequent impact on melanoma-associated vascular normalization, as previously demonstrated." (PMID 34299131, 2021). "Since the expression of the EMILIN2 gene was shown to be down-modulated by methylation in a number of epithelial cancers, we first evaluated if the same epigenetic downregulation could also take place in melanoma patients." (PMID 34299131, 2021). "To determine whether EMILIN2 could predict the therapeutic efficacy in melanoma patients treated with checkpoint inhibitors, we analyzed the EMILIN2 levels in a well-documented cohort of melanoma patients treated with PD-L1 inhibitors (GSE782209)." (PMID 34299131, 2021). "We verified that EMILIN2 also undergoes epigenetic modifications in this cancer type and, notably, some methylation sites were predominant in melanoma as opposed to normal skin." (PMID 34299131, 2021). "Since our results indicate that EMILIN-2 does not directly affect the expression of PD-L1 in melanoma cells, it is conceivable that it could suppress the production of such cytokines in immune cells." (PMID 34299131, 2021).
ovarian carcinoma (2 papers, 2008 to 2011). A malignant neoplasm originating from the surface ovarian epithelium. "In conclusion, using a novel type of biotinylated recombinant antibodies that we call biobodies, we identified complement catabolitic products, EMILIN2, Von Willebrand factor and PEBP1 or a related protein, as candidate markers for ovarian carcinoma." (PMID 18652693, 2008).
porokeratosis (2 papers, 2013 to 2016). A clonal proliferation of abnormal keratinocytes characterized by the development of localized or multiple atrophic skin patches surrounded by an annular keratotic ring called cornoid lamella. "Elastin Microfibril Interfacer 2 (EMILIN2) is a protein-coding gene and is associated with porokeratosis of mibelli and porokeratosis diseases." (PMID 26930047, 2016). "We could speculate that, at least in our family, the duplication of EMILIN2 gene may cause an excessive death receptors activation in the skin and an abnormal apoptosis of epidermal keratinocytes leading to the alteration of the process of keratinization which is at the basis of porokeratosis." (PMID 23593459, 2013).
autosomal dominant non syndromic hearing loss (1 paper, 2014). "Especially for genes whose mutations cause autosomal dominant non syndromic hearing loss (Pou4f3, Slc17a8, Tmc1, and Crym) as well as genes important for cochlear function (Emilin-2 and Tectb), gradual expression changes may help to explain the various pathological conditions." (PMID 24676347, 2014).
brain arteriovenous malformations (1 paper, 2011). "A recent study reported down-regulation of EMILIN2 in brain arteriovenous malformations." (PMID 21569335, 2011).
breast tumours (1 paper, 2010). "To confirm that the methylation of EMILIN2 is functionally relevant, we determined EMILIN2 expression in a subset of primary breast tumours (good quality RNA was available for these samples) using quantitative real-time RT-PCR." (PMID 20205715, 2010). "Expression analysis revealed that the breast tumours with EMILIN2 methylation showed lower levels of EMILIN2 expression compared to unmethylated tumours." (PMID 20205715, 2010). "Using a combination of COBRA and sequencing of bisulphite modified DNA, we confirmed 5 novel genes frequently methylated in breast tumours; EMILIN2, SALL1, DBC1, FBLN2 and CIDE-A." (PMID 20205715, 2010).
cholangiocarcinoma (1 paper, 2022). A carcinoma that arises from the intrahepatic biliary tree (intrahepatic cholangiocarcinoma) or from the junction, or adjacent to the junction, of the right and left hepatic ducts (hilar cholangiocarcinoma). "For example, EMILIN2 expression was significantly up-regulated in cholangiocarcinoma, colon adenocarcinoma, and ccRCC." (PMID 36544490, 2022).
clear cell renal cell carcinoma (1 paper, 2022). "Patients with clear cell renal cell carcinoma were grouped according to EMILIN2 expression, and the intersection of genes showing differential expression in different groups and subtypes was obtained." (PMID 36544490, 2022). "Nevertheless, the mechanism of action of EMILIN2 in clear cell renal cell carcinoma (ccRCC) remains unclear." (PMID 36544490, 2022).
colitis (1 paper, 2022). Inflammation of the colon. "Accordingly, Emilin-2 null mice displayed increased susceptibility to colitis-associated tumorigenesis and worse outcome." (PMID 35148799, 2022). "Alteration of macrophages in Emilin-2−/− mice were observed both in the sporadic and in colitis associated CRC models." (PMID 35148799, 2022).
colon cancer (1 paper, 2022). "In fact, the proliferation and apoptotic rate of tumor cells grown in Emilin-2−/− mice was not altered, consistent with the results obtained using human colon cancer cells challenged with EMILIN-2." (PMID 35148799, 2022).
Colorectal tumour (1 paper, 2010). "Colorectal tumour lines showed frequent methylation of all 5 genes, whilst prostate tumour lines demonstrated frequent methylation of CIDE-A, DBC1, EMILIN2, SALL1 and less frequent methylation for FBLN2." (PMID 20205715, 2010).
diffuse astrocytoma (1 paper, 2020). A low-grade (WHO grade II) astrocytic neoplasm. "We found that EMILIN1 and EMILIN2 were overexpressed in diffuse astrocytoma compared to normal brain tissue." (PMID 32175193, 2020).
fibrosis (1 paper, 2024). the formation of excess fibrous connective tissue in an organ or tissue in a reparative or reactive process. "In patients with scleroderma and the bleomycin-induced murine fibrosis model EMILIN-2 was upregulated." (PMID 39639116, 2024).
fracture (1 paper, 2024). "Therefore, Emilin2 can be used for the treatment of bone fracture by recruiting endogenous progenitor cells." (PMID 38831448, 2024). "Finally, in light of the clinical application of Emilin2 for the treatment of bone fracture, recombinant Emilin2 was introduced to the injury site using a collagen carrier, at the same time as macrophage depletion in the bone-surrounding tissue." (PMID 38831448, 2024).
gastric tumors (1 paper, 2018). "Interestingly, when EMILIN-2 expression was strongly decreased in gastric tumor samples, the organization of the EMILIN-1 fibers was also altered." (PMID 30544909, 2018). "Given that both blood and lymphatic vessels represent a route for metastatic cell dissemination, the altered expression of EMILIN-2 and EMILIN-1 may significantly impact of the progression of gastric tumors." (PMID 30544909, 2018).
head-neck cancers (1 paper, 2023). "Emilin2 is already known as a poor prognostic marker for liver cancer and a poor prognostic marker for renal and head-neck cancers." (PMID 37775701, 2023).
inflammatory bowel disease (1 paper, 2022). A spectrum of small and large bowel inflammatory diseases of unknown etiology. "These analyses indicated that EMILIN-2 gene is down-modulated also in the context of inflammatory bowel diseases (IBD)." (PMID 35148799, 2022).
ovarian serous tumor (1 paper, 2008). A benign, borderline, or malignant epithelial tumor of the ovary characterized by the presence of neoplastic epithelial cells that, in well differentiated tumors, resemble the epithelial cells of the fallopian tube and, in poorly differentiated tumors, show anaplastic features. "Interestingly, EMILIN2 has been found to play a role in trophoblast invasion of the uterine wall and is enriched at the level of mRNA expression in ovarian serous tumors, and Von Willebrand factor has been associated with multiple cancers." (PMID 18652693, 2008).